SLC7A11 (solute carrier family 7 member 11)
Diseases named in the same sentence as SLC7A11 in open-access papers (continued):
Sharing a sentence is not in itself a finding about the gene and the disease.
schizophrenia (7 papers, 2017 to 2025). A major psychotic disorder characterized by abnormalities in the perception or expression of reality. "To briefly conclude, we propose that system xc− subunits can serve as a diagnostic tool for schizophrenia based on the study of mRNA SLC7A11, and SLC3A2." (PMID 34575878, 2021). "Considering the impact of schizophrenia in neurotransmission metabolism, we found that SLC7A11, which plays critical roles in glutamine metabolism, was increased in males." (PMID 39068467, 2024). "We thus measured the mRNA expression levels of SLC3A2 and SLC7A11 in peripheral white blood cells in well-characterized, unrelated patients with schizophrenia and healthy controls." (PMID 34575878, 2021). "The relationship between xc− and schizophrenia pathogenesis was investigated in a recent study, in which the mRNA expression of SLC7A11 and SLC3A2 in peripheral white blood cells was discovered to be lower in patients with schizophrenia than in healthy people." (PMID 34575878, 2021). "Research on the mRNA expression of SLC7A11 and SLC3A2 has revealed that diagnostic tools for schizophrenia in a clinical setting must be validated." (PMID 34575878, 2021). "In peripheral white blood cells from schizophrenia patients, the Slc7a11 expression was lower compared to those from healthy donors." (PMID 32587657, 2020). "The peripheral mRNA expression levels of two system xc− subunits, SLC7A11 and SLC3A2 (particularly SLC3A2), are decreased in patients with schizophrenia." (PMID 34575878, 2021). "According to the review of the literature, decreased mRNA expression of system xc− subunits SLC7A11 and SLC3A2 in patients with schizophrenia supports the hypoglutamatergic neurotransmission hypothesis regarding the pathogenesis of schizophrenia." (PMID 34575878, 2021). "From the perspective of the hypoglutamatergic hypothesis and experimental evidence, decreased mRNA expression levels of SLC7A11 and SLC3A2 in peripheral blood could be developed as accurate tools for diagnosing schizophrenia." (PMID 34575878, 2021). "Hence, the current review indicates an effective association and provides clear evidence that system xc− subunits SLC7A11 and SLC3A2 may serve as important biomarkers for schizophrenia." (PMID 34575878, 2021).
ulcerative colitis (7 papers, 2021 to 2026). An inflammatory bowel disease involving the mucosal surface of the large intestine and rectum. "In this study, we demonstrated that PD effectively protects against DSS-induced ulcerative colitis both in vitro and in vivo, elucidating its potential mechanism through Nrf2/Slc7a11/Gpx4-dependent inhibition of ferroptosis signaling pathways." (PMID 39877390, 2024). "Our study suggested that PD protects against DSS-induced ulcerative colitis via Nrf2/Slc7a11/Gpx4-dependent inhibition of ferroptosis signalling activation." (PMID 39877390, 2024). "Targeting SLC7A11 augments dendritic cell efferocytosis and preserves intestinal epithelial barrier function, potentially offering a therapeutic avenue for alleviating ulcerative colitis." (PMID 40360947, 2025). "Furthermore, the expression levels of the glutamate–cystine antiporter SLC7A11 and the cystine abundance in the intestinal mucosa of IBD patients exhibit pronounced upregulation in ulcerative colitis (UC) tissue relative to healthy controls." (PMID 40428318, 2025). "In vitro, colon tissues from patients with ulcerative colitis were analyzed to compare SLC7A11 expression between inflamed and non-inflamed regions." (PMID 40360947, 2025).
viral infection (7 papers, 2010 to 2025). "In viral infections, Hepatitis B virus induces ferroptosis in hepatocytes by inhibiting SLC7A11 expression, causing liver failure, while SLC7A11 overexpression or ferroptosis inhibitors can rescue these cells." (PMID 40617807, 2025). "It establishes contacts with the chromatin of human GM12878 cells, specifically targeting the SLC7A11 gene, which is involved in inhibiting viral infection, in the region on chromosome 4 via RNAPII-associated chromatin loops (left panel and EV3A)." (PMID 40425856, 2025). "Additionally, the study observed that viral infection increases the expression levels of ACSL4, FTH1, and SLC7A11, but they gradually decrease as the viral infection progresses." (PMID 40661982, 2025). "The overexpression of NRF2 enhanced the expression of SLC7A11 and GPX4 in A549 cells and alleviated ferroptosis induced by virus infection." (PMID 38542289, 2024). "This suggests that viral infection may upregulate ACSL4, activating ferroptosis, but it also upregulates the expression of SLC7A11 and FTH1 to inhibit the ferroptosis process." (PMID 40661982, 2025). "In addition, we found that the protein expression levels of NRF2, SLC7A11, and GPX4 were down-regulated after viral infection." (PMID 38542289, 2024). "As the viral infection progresses, the cell initiates a negative feedback mechanism to resist the virus’s control over the ferroptosis process, resulting in decreased expression of ACSL4 and SLC7A11." (PMID 40661982, 2025).
Anxiety (6 papers, 2017 to 2024). Intense feelings of nervousness, tension, or panic often arise in response to interpersonal stresses. "Analysis of behavior in the EPM demonstrated that both male and female SLC7A11sut/sut mice show increased open-space anxiety compared to male and female SLC7A11+/+ mice." (PMID 37649973, 2023). "Interestingly, open-space anxiety and deficits in sociability emerge with age in SLC7A11+/+ female mice." (PMID 37649973, 2023). "Then, we found the proteins expression of GPX4, SLC7A11, FTH, ACSL4 and FPN, which were also significantly reduced in depressive and anxiety-like behavioral mice whose symptoms were induced by alcohol." (PMID 36430312, 2022). "However, female SLC7A11sut/sut mice at both ages displayed open-space anxiety as demonstrated by a reduction in both the number of entries and time spent in the open arms of an EPM when compared to their age- and sex-matched SLC7A11+/+ littermate controls." (PMID 37649973, 2023). "Similar to findings in male SLC7A11+/+ mice, age did not enhance open-space anxiety in either male or female SLC7A11sut/sut mice." (PMID 37649973, 2023). "Finally, age significantly worsened open-space anxiety in SLC7A11+/+ female mice — but not male SLC7A11+/+ mice — as demonstrated by significant reduction in the number of entries into open arms and the percent time spent in the open arms when compared to when they were young." (PMID 37649973, 2023).
brain cancer (6 papers, 2016 to 2025). A primary or metastatic malignant neoplasm affecting the brain. "SLC7A11 is a crucial biomarker in neurodegenerative diseases and brain cancers, and overexpression of SLC7A11 results in an imbalance in cellular glutamate homeostasis." (PMID 40636521, 2025). "Thus, the alterations of Slc7a11 gene are closely related to alterations of Slc7a11 gene, not only in mice but also in human brain cancer patients." (PMID 34187574, 2021).
endothelial dysfunction (6 papers, 2013 to 2024). In vascular diseases, endothelial dysfunction is a systemic pathological state of the endothelium (the inner lining of blood vessels) and can be broadly defined as an imbalance between vasodilating and vasoconstricting substances produced by (or acting on) the endothelium. "The activation of the cysteine-glutamate transporter (encoded by SLC7A11) and the increased glutamate level as a response to oxidative stress is also of great importance to endothelial dysfunction involved at all stages of atherosclerotic plaque evolution, which leads to CVD." (PMID 23497222, 2013). "In mouse aortic endothelial cells (MAECs), ox-LDL causes mitochondrial damage and decreases the expression of SLC7A11 and GPX4, whereas Fer-1 can suppress ox-LDL induced lipid peroxidation and endothelial dysfunction." (PMID 35906548, 2022). "Additionally, ox-LDL causes mitochondrial damage and downregulates the expressions of SLC7A11 and GPX4 in mouse aortic endothelial cells (MAECs), while Fer-1 could repress ox-LDL-induced lipid peroxidation and endothelial dysfunction in MAECs." (PMID 34368260, 2021).
gastric adenocarcinoma (6 papers, 2020 to 2025). "Consistent with the results in H. pylori-infected cells and INS-GAS mice, we found that the gene levels of IL-32, RELB and SLC7A11 were significantly increased in stomach adenocarcinoma tissues compared with those in normal tissues." (PMID 32457731, 2020).
lymph node metastasis (6 papers, 2021 to 2025). "There are results indicating that SLC7A11 overexpression is strongly associated with lymph node metastasis, short survival times, and poor treatment response." (PMID 39335604, 2024). "NRF2 nuclear expression was significantly associated with tumor length, lymph node metastasis, and TNM stage, while SLC7A11 expression was associated with lymph node metastasis." (PMID 34446045, 2021). "The proportion of SLC7A11-positive patients tended towards high lymph node metastasis rates." (PMID 34446045, 2021).
malignant glioma (6 papers, 2014 to 2025). A grade III or grade IV glioma arising from the central nervous system. "SLC7A11 expression is associated with accelerated growth and tumor-associated seizures and predicts poor survival in patients with malignant glioma." (PMID 30558624, 2018).
chronic lymphocytic leukemia (5 papers, 2018 to 2025). "Interestingly, SLC7A11 was down-regulated in chronic lymphocytic leukemia (CLL) compared with other systemic solid tumors." (PMID 37139157, 2023). "For example, bone marrow stromal cells surrounding chronic lymphocytic leukemia (CLL) cells secrete large amounts of cysteine, which are directly imported by ASC on the plasma membrane of CLL cells despite low expression of SLC7A11 in CLL cells." (PMID 29764521, 2018).
endometriosis (5 papers, 2023 to 2025). The growth of functional endometrial tissue in anatomic sites outside the uterine body. "To explore the mechanism responsible for the IL-33/ST2-mediated activation of SLC7A11 in endometriosis, we first identified differentially expressed genes (DEGs) using an endometriosis dataset obtained from the GEO database (GSE19834)." (PMID 37816731, 2023). "Furthermore, overexpression of SLC7A11 (solute carrier family 7 member 11) in endometriosis enables cells to escape iron-dependent ferroptosis, allowing ectopic cells to survive even under oxidative stress." (PMID 41009686, 2025). "Moreover, macrophage-derived IL-33/ST2 has been shown to inhibit ferroptosis in endometriosis through the ATF3/SLC7A11 axis, indicating that macrophages may influence endometriosis ferroptosis via SLC regulation." (PMID 41150779, 2025). "Hence, we aimed to test whether ATF3 participates in the IL-33-mediated upregulation of SLC7A11 in endometriosis." (PMID 37816731, 2023). "In endometriosis, IL-33/ST2 inhibits ATF3 by activating the p38/JNK signaling pathway, thereby upregulating the expression of SLC7A11, reducing ferroptosis, and protecting endometriotic stromal cells (eESCs) from damage." (PMID 41550926, 2025).
keloid (5 papers, 2024 to 2025). An irregularly shaped, elevated mark on the skin caused by deposits of excessive amounts of collagen during wound healing. "A therapy against keloid induces ferroptosis in keloid fibroblasts via ROS, accompanied by downregulation of SLC7A11 and GPX4." (PMID 39958433, 2025). "The effect of solute carrier family 7-member 11 (SLC7A11) silencing on ADSC-Exo-treated keloid fibroblast was investigated." (PMID 39221144, 2024). "Compared with those of the controls, ADSC-Exos and ADSC-Exos cocultured with si-NC KF inhibited the expression of fibrosis-related genes in keloids and increased the protein expression of SLC7A11 and GPX4." (PMID 39221144, 2024). "Our results implicated that SLC7A11, GPX4, and Nrf2 were remarkably downregulated and TFRC upregulated in keloid tissues." (PMID 38887622, 2024). "Then, our RT-qPCR analysis implicated that SLC7A11 (P < 0.001), GPX4 (P < 0.001), and Nrf2 mRNA (P < 0.001) levels were decreased and TFRC mRNA level was increased in keloid tissues." (PMID 38887622, 2024). "Additionally, iron has been demonstrated to accumulate in keloid tissue, along with significant downregulation of SLC7A11, GPX4, and Nrf2 and upregulation of transferrin receptor protein 1 (TFRC)." (PMID 39958433, 2025). "To explore whether ferroptosis is involved in keloid development, we collected keloid tissues (n = 70) from keloid patients and normal skin tissues from healthy controls (n = 40), and iron content and SLC7A11, GPX4, Nrf2 and TFRC levels were determined." (PMID 38887622, 2024). "We hypothesized that the increase in GPX4 signaling in keloids may be mediated by exosomes that increase the expression of SLC7A11 in keloids." (PMID 39221144, 2024). "SLC7A11, GPX4, and Nrf2 were downregulated and TFRC was upregulated in keloid tissues and KFs." (PMID 38887622, 2024). "SLC7A11, GPX4, and Nrf2 were significantly downregulated and TFRC upregulated in keloid tissues." (PMID 38887622, 2024). "Furthermore, SLC7A11 (P < 0.001), GPX4 (P < 0.001), and Nrf2 (P < 0.001) protein levels were significantly downregulated and TFRC protein level was (P < 0.001) upregulated in keloid tissues." (PMID 38887622, 2024).
liver cirrhosis (5 papers, 2022 to 2025). "Univariate analysis indicated that liver cirrhosis, the BCLC stage, and the SLC7A11 expression level are significant risk factors affecting prognosis in patients with HCC (p < 0.001)." (PMID 40978058, 2025). "SLC7A11 levels were also shown to be a complementary marker for alpha fetoprotein (AFP) levels in the diagnosis of HCC from liver cirrhosis." (PMID 39335604, 2024). "Compared with the liver cirrhosis tissues, SLC7A11 was also significantly upregulated and STEAP3 was downregulated in HCC (GSE45050)." (PMID 36229881, 2022). "For the DEN-induced rat model database, we found that the expression level of the SLC7A11 gene was higher in HCC than in liver hepatitis (LH), liver cirrhosis (LC), and normal control (NC)." (PMID 39744233, 2025).
papillary thyroid carcinoma (5 papers, 2022 to 2025). "FTO is able to inhibit the occurrence of papillary thyroid carcinoma by downregulating SLC7A11 in m6A independently." (PMID 38200441, 2024). "Transwell migration and invasion experiments also proved the ability of SLC7A11 overexpression to promote the migration and invasion of papillary thyroid cancer cells, while SLC7A11 knockdown cells showed the adverse effect." (PMID 35721711, 2022). "Upon combination analysis of meRIP-Seq and RNA-Seq and selection of SLC7A11, it is speculated that SLC7A11 may be used as a downstream target gene of FTO to regulate papillary thyroid carcinoma." (PMID 35721711, 2022). "For instance, inhibition of solute carrier family 7 member 11 (SLC7A11), an essential ferroptosis suppressor, could alleviate PTC (papillary thyroid cancer) progression." (PMID 40862294, 2025).
psoriasis (5 papers, 2021 to 2023). An autoimmune condition characterized by red, well-delineated plaques with silvery scales that are usually on the extensor surfaces and scalp. "The transport of inorganic ions and amino acids pathway related to psoriasis risk includes the SLC7A11 gene." (PMID 34707088, 2021). "Although recent reports support some of our conjectures, the role of SLC7A11 in regulating psoriasis and ferroptosis needs further study." (PMID 36276287, 2022). "More importantly, SLC7A11 is positively correlated with psoriasis." (PMID 36856826, 2023). "Thus, our results indicate SLC7A5, SLC7A11, and CHAC1 as the underlying biomarkers for psoriasis, providing further evidence about the crucial role of ferroptosis in psoriasis." (PMID 36276287, 2022). "Interestingly, in our study, the expression of SLC7A11 mRNA in psoriasis lesions was upregulated, in accordance with a previous report on ferroptosis in psoriasis." (PMID 36276287, 2022). "Many reports have shown that SLC7A11-mediated regulation of ferroptosis plays a crucial role in cancers, while several cancer immunotherapy methods that are also effective in treating psoriasis show the significance of inhibiting SLC7A11 and inducing ferroptosis in tumor cells." (PMID 36276287, 2022). "Similar to the results of paired samples in the GSE30999 dataset, the expression levels of SLC7A5, SLC7A11, and CHAC1 were increased in the psoriasis lesions (1.85-, 1.73- and 1.70-fold, respectively) compared to normal skin tissues." (PMID 36276287, 2022). "Psoriasis-related compounds corresponding to SLC7A5 and SLC7A11 were also identified, including Melphalan, Quisqualate, Riluzole, and Sulfasalazine." (PMID 36276287, 2022). "SLC7A5, SLC7A11, and CHAC1 may affect the development of psoriasis by regulating ferroptosis." (PMID 36276287, 2022). "However, no direct evidence exists that SLC7A11 is related to psoriasis by mediating ferroptosis." (PMID 36276287, 2022).
sarcoma (5 papers, 2017 to 2024). A usually aggressive malignant neoplasm of the soft tissue or bone. "This study identified three valuable genes (SLC7A11, RPN1, GYS1) associated with disulfidptosis in sarcoma (SARC) and developed a prognostic model." (PMID 38531930, 2024). "Compared to their corresponding normal cell lines, SLC7A11, RPN1, and GYS1 exhibited significantly upregulated mRNA expression in sarcoma cell lines (143B, SW982, and SW872)." (PMID 38531930, 2024). "The SLC7A11 protein was expressed at a high level in HDF, 293T cells, and U2OS sarcoma cells while the expression of GPX4 protein was high in HDF, Aska and Yamato cell lines." (PMID 37444594, 2023). "Erastin, an inhibitor of the cystine–glutamate antiporter SLC7A11, had a strong cytotoxic effect on sarcoma cell lines as well as noncancer and carcinoma cell lines." (PMID 37444594, 2023).
alcohol use disorders (4 papers, 2014 to 2023). "Increased expression SLC7A11 was associated with poor prognosis in cancer, alcohol use disorders, and increased BP." (PMID 36360196, 2022). "The top EWAS probe cg06690548, mapped to cystine/glutamate transporter SLC7A11, was replicated in the second cohort of alcohol use disorders (AUD) and control participants showing strong hypomethylation in AUD (P < 1E-17)." (PMID 36873949, 2023).
Cirrhosis (4 papers, 2011 to 2025). A chronic disorder of the liver in which liver tissue becomes scarred and is partially replaced by regenerative nodules and fibrotic tissue resulting in loss of liver function. "The mRNA expression of STEAP3 was significantly downregulated in HCV-infected cirrhotic HCC compared with the cirrhosis tissues, and SLC7A11 was no significant in HCV-infected cirrhotic HCC." (PMID 36229881, 2022).
cystinuria (4 papers, 2022 to 2025). Cystinuria is a renal tubular amino acid transport disorder characterized by recurrent formation of kidneys cystine stones. "In genetic disorders, cystinuria is caused by mutations in SLC7A9/SLC3A1, leading to dysfunction of the cystine/glutamate antiporter (SLC7A11/xCT) and defective renal tubular cystine reabsorption, compounded by insufficient compensatory activity of the NADPH-dependent disulfide reductase system." (PMID 40295497, 2025). "In mammals, transporters such as the heterodimeric amino acid transporter b0, +AT (SLC7A9), the cystine‐glutamate antiporter xCT (SLC7A11) and AGT‐1 (SLC7A13) play key roles in redox homeostasis and are implicated in various disorders including cancer and cystinuria." (PMID 41229165, 2025). "The loss of Slc7a11-dependent cystine uptake increased the susceptibility to ROS in Slc7a11-deleted mice, while renal stones, which are frequently caused by cystinuria, were not seen, suggesting xCT is not critical in reabsorption of filtrated cystine." (PMID 35326646, 2022).